HAVCR2 (hepatitis A virus cellular receptor 2)
Diseases named in the same sentence as HAVCR2 in open-access papers (continued):
Sharing a sentence is not in itself a finding about the gene and the disease.
esophageal cancer (19 papers, 2016 to 2025). A primary or metastatic malignant neoplasm involving the esophagus. "Higher HAVCR2 gene expression was associated with a lower risk in uveal melanoma (UVM), LGG, thymoma (THYM), and esophageal carcinoma (ESCA), but higher in cervical squamous cell carcinoma and endocervical adenocarcinoma (CESC) and SKCM." (PMID 36354714, 2022). "In the TISIDB database, ENTPD1 expression in esophageal carcinoma was shown to be statistically positively correlated with the expression of currently recognized inhibitory immune checkpoint molecules PDCD1 (p < 0.001), CTLA4 (p < 0.001), and HAVCR2 (p < 0.001)." (PMID 36831526, 2023). "Moreover, we found that the expression level of ENTPD1 was positively correlated with the infiltrating abundance of CD8+ T cells and the expression level of inhibitory immune checkpoint molecules PDCD1, CTLA4, and HAVCR2 in esophageal carcinoma, but not in normal tissues." (PMID 36831526, 2023).
atherosclerosis (18 papers, 2014 to 2025). A disease characterized by the build-up of fatty material and calcium deposition in the arterial wall resulting in partial or complete occlusion of the arterial lumen. "RBM47, HCK, CD53, TYROBP, and HAVCR2 were identified as common hub genes, which were validated to be upregulated in advanced atherosclerotic plaques, to well distinguish CAD patients from non-CAD people and to regulate immune cell function-related mechanisms in advanced atherosclerosis." (PMID 33519905, 2020).
asthma (16 papers, 2009 to 2026). "To address the potential role of Tim3 in experimental asthma, we developed a mouse line deficient for Tim3 (Havcr2) by gene targeting in ES cells." (PMID 21470319, 2011).
mesothelioma (16 papers, 2013 to 2026). A usually malignant and aggressive neoplasm of the mesothelium which is often associated with exposure to asbestos. "IRF3 expression and the immune checkpoint genes significantly correlated with LAG3 and LGALS1 (Galectin) genes expression in mesothelioma cells, while positive correlation was found between IRF3 and HAVCR2 (TIM-3) or PDCD1LG2 (PD-L2) expression in monocytes/macrophages." (PMID 34768716, 2021). "Additional co-inhibitory and co-stimulatory molecules such as T-cell immunoglobulin and mucin-domain containing-3 (TIM3, also known as HAVCR2), lymphocyte activation gene 3 (LAG3) and inducible T cell co-stimulator (ICOS) are being investigated in mesothelioma." (PMID 32226777, 2020).
Miscarriage (16 papers, 2015 to 2024). A pregnancy that ends at a stage in which the fetus is incapable of surviving on its own, defined as the spontaneous loss of a fetus before the 22th week of pregnancy. "The percentage of uNK cells with HAVCR2 expression is decreased in human miscarriages and abortion-prone murine models." (PMID 33477602, 2021). "Moreover, decreased Th2-cytokine and increased Th1-cytokine levels are observed in uNK cells with HAVCR2 expression, but not in those without HAVCR2 expression from human and murine miscarriages." (PMID 33477602, 2021).
T cell lymphoma (15 papers, 2013 to 2026). "The c.A291G; p.I97M HAVCR2/TIM-3 mutation has been demonstrated to encode a loss of function allele and has, in homozygous but also in heterozygous states, been shown to cause subcutaneous panniculitis-like T cell lymphoma (SPTCL) and autoinflammatory disease." (PMID 38363399, 2024). "For instance, a novel association between HLH and loss-of-function mutations in the HAVCR2 gene (coding for T cell immunoglobulin and mucin domain-containing protein 3 (TIM-3)) was identified in patients with subcutaneous panniculitis-like T cell lymphoma with associated HLH." (PMID 37187762, 2023). "Subcutaneous panniculitis-like T-cell lymphoma (SPTCL) is a rare subtype of non-Hodgkin lymphoma associated with hemophagocytic lymphohistiocytosis (HLH)/HLH-like systemic illnesses and germline HAVCR2 mutations." (PMID 39538229, 2024). "Germline mutations of HAVCR2, leading to the loss of function of TIM3, were proven to promote the disease development of subcutaneous panniculitis-like T-cell lymphoma." (PMID 35625999, 2022). "While these findings raised strong concern for subcutaneous panniculitis-like T-cell lymphoma (SPTCL), definitive diagnosis was precluded by the absence of immunophenotyping, T-cell receptor clonality studies, and HAVCR2 mutation testing-all unavailable in our setting." (PMID 42078049, 2026). "TIM3 deficiency (OMIM #618398) caused by HAVCR2 mutations is another autosomal-recessive inborn error of immunity that predisposes to HLH in a particular context, i.e., in subcutaneous panniculitis T cell lymphoma (SPTCL)." (PMID 32457750, 2020).
colitis (14 papers, 2018 to 2026). Inflammation of the colon. "Ctla4 was the most highly upregulated checkpoint gene in all the colitis models, with less pronounced changes in the expression of Pdcd1, Lag3, Vsir and Havcr2." (PMID 39496592, 2024).
nasopharyngeal carcinoma (13 papers, 2011 to 2025). A carcinoma arising from the nasopharyngeal epithelium. "We found a mutual positive association between TOX and TOX2, TOX and HAVCR2, and TOX2 and HAVCR2 at the transcriptional level in CD3+ tumor-infiltrating T cells (TILs) in single cell (sc)RNA-sequencing of nasopharyngeal carcinoma samples." (PMID 39080376, 2024).
liver fibrosis (11 papers, 2013 to 2025). "The NASH and liver fibrosis score also showed that Havcr2 knockdown mice had lower levels of NASH fibrosis than wild-type mice." (PMID 40251185, 2025).
Obesity (11 papers, 2020 to 2026). Accumulation of substantial excess body fat. "Jude PeCan Data Portal which revealed that the HAVCR2 gene is expressed at low levels in several B-ALL subtypes compared to levels found in healthy PBMCs, as well as our patient data demonstrating similar TIM3 surface levels on human B-ALL cells isolated from lean patients and patients with obesity." (PMID 35241678, 2022). "In contrast, the expression of HAVCR2 was not significantly different in B-ALL cells from lean patients and patients with obesity." (PMID 35241678, 2022).
hepatitis C virus infection (9 papers, 2014 to 2024). A viral infection caused by the hepatitis C virus. "Some previous studies also indicated that PDCD1, CTLA4, and HAVCR2 polymorphisms were sex-dependently associated with MAC-LD risk, the resolution of hepatitis C virus infection, and the outcomes of HCV infection, respectively." (PMID 38723011, 2024).
ovarian tumors (9 papers, 2020 to 2025). "It was found that in recurrent ovarian tumors there was a higher gene expression of LAG-3, HAVCR2 (TIM3), TIGIT and CTLA-4 than in primary tumors." (PMID 36077354, 2022). "The ovarian tumors showed high gene expression of LAG3 and HAVCR2 (TIM3) and enhanced levels of TIGIT and CTLA4 in recurrent tumors compared to primary tumors." (PMID 33352957, 2020).
parasitemia (9 papers, 2017 to 2026). "From this, we identified 26 common DEGs downregulated in Tr1 cells from both parasitic diseases, including Ccr7, Tcf7, and Bcl6, as well as 29 upregulated DEGs, including Il10, Havcr2, Prdm1, Ccr2, Ccr5, Maf, and Lag3." (PMID 37917177, 2023).
psoriasis (9 papers, 2020 to 2025). An autoimmune condition characterized by red, well-delineated plaques with silvery scales that are usually on the extensor surfaces and scalp. "In addition to the cytokines noted above such as IL17F (0.967), and CXCL13 (0.325), this set contained identified psoriasis-specific genes with less established functional roles, such as ARHGEF12 (0.303), ENTPD1 (0.628), LAYN (0.122) and HAVCR2 (0.560)." (PMID 35958578, 2022).
brain tumors (8 papers, 2019 to 2025). "We hypothesized that AQP4 could also be the regulatory factors of various immune checkpoints in brain tumors, such as TIM-3 (HAVCR2), PD-L1 (CD274), PD-L2 (PDCD1LG2), and CEACAM1." (PMID 34113257, 2021).
colon adenocarcinoma (8 papers, 2015 to 2025). "Notably, higher expressions of CTLA4 and PD1 were associated with improved survival, while higher TIL load correlated with CTLA4, HAVCR2 (TIM-3), LAG3, and CD274 (PD-L1) expressions in colon adenocarcinoma." (PMID 35804964, 2022).
endometrial cancer (8 papers, 2019 to 2025). Primary or metastatic malignant neoplasm involving the endometrium (mucous membrane that lines the endometrial cavity). "First, we included the expression profile data of all normal endometrial samples and endometrial cancer samples of TCGA and observed the expression levels of common immune checkpoints, including PDCD1, CD274 (PDL1), PDCD1LG2 (PDL2), CTLA4, LAG3, and HAVCR2." (PMID 37872211, 2023).
thymoma (8 papers, 2015 to 2023). A neoplasm arising from the epithelial cells of the thymus. "However, low HAVCR2 expression was observed in five tumor types: adrenocortical carcinoma (ACC), kidney chromophobe (KICH), LUAD, LUSC, and thymoma (THYM)." (PMID 36081997, 2022).
hemophagocytic lymphohistiocytosis (7 papers, 2021 to 2024). "Patients with HAVCR2 mutation are younger (<30 years), often associated with hemophagocytic lymphohistiocytosis (HLH) and worse prognosis." (PMID 37747559, 2024). "Cases with a severe haemophagocytic syndrome are significantly linked with germline mutations in HAVCR2 gene encoding T-cell immunoglobulin mucin-3 (TIM-3), an inhibitory receptor expressed on T-cells and innate immune cells." (PMID 34449587, 2021).
kidney cancer (7 papers, 2016 to 2026). Primary or metastatic malignant neoplasm involving the kidney. "Methylation levels in the promoter of HAVCR2 were associated with poor prognosis in kidney cancers (KIRC and KIRP), ACC, UCS, UVM, and LGG." (PMID 40076932, 2025).
non-Hodgkin lymphoma (7 papers, 2013 to 2025). Distinct from Hodgkin lymphoma both morphologically and biologically, non-Hodgkin lymphoma (NHL) is characterized by the absence of Reed-Sternberg cells, can occur at any age, and usually presents as a localized or generalized lymphadenopathy associated with fever and weight loss. "One of the strong pieces of evidence implicating TIM-3 as an immune checkpoint receptor came from independent studies of germline loss-of-function mutations (Tyr82Cys or Ile97Met) of HAVCR2 (encoding TIM-3) in non-Hodgkin lymphoma patients." (PMID 41031910, 2025).
Arthritis (6 papers, 2018 to 2025). Inflammation of a joint. "LGALS9 encodes galectin‐9, one of four ligands for the immune checkpoint receptor TIM‐3, also known as hepatitis A virus cellular receptor 2; blockade of TIM‐3 ameliorates arthritis in a mouse model." (PMID 39887658, 2025).
chordoma (6 papers, 2020 to 2024). Chordomas are rare malignant tumors arising from embryonic remnants of the notochord in axial skeleton. "Despite the elevated proportion of Tregs observed in recurrent chordomas, the cells exhibited significant expression of TIGHT, CTLA4, PDCD1, ENTPD1 and HAVCR2, indicating the immunosuppressive nature of Tregs." (PMID 37784253, 2023).
cutaneous melanoma (6 papers, 2020 to 2023). A primary melanoma arising from atypical melanocytes in the skin. "Furthermore, CD274 (PD-L1) expression correlated significantly with the rest immune checkpoints (apart from VTCN1) in skin melanoma compared to normal skin (not exposed to the sun), especially with PD-L2, ILT2, HAVCR2 and TIGIT." (PMID 36389735, 2022).
gastric tumor (5 papers, 2013 to 2025). "Our analysis revealed that both LGALS9 and HAVCR2 are upregulated in gastric tumors and associated with poor patient survival." (PMID 40666515, 2025). "The interaction between EP11-CLDN7 and CD8+ T cells was dominated by the interactions of LGALS9—HAVCR2 and HVEM—CD160 both of which are well-known checkpoints that inhibit CD8 + T cell functionality, suggesting an immunosuppressive function of the gastric tumor cells." (PMID 36550535, 2022).
intracerebral hemorrhage (5 papers, 2019 to 2026). A cerebrovascular disorder characterized by bleeding into one or both cerebral hemispheres including the basal ganglia and the cerebral cortex. "The role of HAVCR2 in nerve injury was shown in patients with spontaneous intracerebral hemorrhage whose increased HAVCR2 expression on CD14+ monocytes was associated with systemic inflammatory response and sub-acute brain injury." (PMID 32140464, 2020).
pneumonia (5 papers, 2020 to 2024). An acute, acute and chronic, or chronic inflammation focally or diffusely affecting the lung parenchyma, caused by an infection in one or both of the lungs (by bacteria, viruses, fungi, or mycoplasma.). "Nevertheless, several of them, SELL, GZMB, and CCR7 (at 3 dpi), and HAVCR2 (TIM-3), TNFRSF9 (CD137), and GPR18 (at 6 dpi) were promptly upregulated for the virulent Lena strain, probably associated with the marked clinical signs, the earlier and stronger peak of replication, and severe pneumonia." (PMID 34851149, 2022).
stomach adenocarcinoma (5 papers, 2019 to 2025). "We performed bioinformatic analysis of The Cancer Genome Atlas (TCGA) stomach adenocarcinoma (STAD) dataset to assess LGALS9 and HAVCR2 expression and their clinical correlations." (PMID 40666515, 2025).
uveal melanoma (5 papers, 2019 to 2025). A melanoma derived from melanocytes of the uveal tract. "Similarly, in uveal melanoma (UVM) and liver hepatocellular carcinoma (LIHC), CRABP2 expression is significantly correlated with seven of these immune checkpoint genes (LAG3, CTLA4, PDCD1LG2, HAVCR2, PDCD1, CD274, and TIGIT)." (PMID 39991584, 2025).
chronic hepatitis (4 papers, 2020 to 2024). An active inflammatory process affecting the liver for more than six months. "Similarly, HAVCR2 and LGALS9 expression of nMac in patients with chronic hepatitis overlapped in patients with HBeAg+ chronic infection." (PMID 39135698, 2024).
Immunodeficiency (4 papers, 2020 to 2025). Failure of the immune system to protect the body adequately from infection, due to the absence or insufficiency of some component process or substance. "Second, genetic immune deficiencies, such as HAVCR2 mutations and X-linked lymphoproliferative disease, may predispose individuals to both cancer and HLH." (PMID 40165892, 2025).
pancreatic adenocarcinoma (4 papers, 2021 to 2023). "“Profile-B” is made by the 6 molecules differently expressed in Pancreatic adenocarcinoma (PAAD) patients (i.e., TIM3 (HAVCR2), OX40 (TNFRSF4), GITR (TNFRRSF18), TIGIT, LAG3 and CTLA4)." (PMID 36224560, 2022).
skin tumors (4 papers, 2019 to 2025). "In addition, this T-cell cluster exhibited over-expression of exhaustion marker genes such as Tox, Pdcd1, Tigit, Havcr2, Lag3, and Ctla4 in the T cell cluster in skin tumors, suggesting the emergence of T-cell exhaustion in skin tumors." (PMID 40282557, 2025).
medullary thyroid carcinoma (3 papers, 2022 to 2024). "A large cohort study discovered that HAVCR2 (TIM-3) was positively expressed in 48% medullary thyroid carcinoma." (PMID 36530988, 2022).
myositis (3 papers, 2022 to 2024). "Next, we colocalized IIM signals that overlapped IMD signals, and found seven potentially novel myositis associations mapped to immune-related genes, including BLK, IRF5/TNPO3, and ITK/HAVCR2, implicating a role for both B and T cells in IIM." (PMID 39044428, 2024).
T-cell acute lymphoblastic leukemia (3 papers, 2024 to 2025). Acute lymphoblastic leukemia of T-cell origin. "The role of CD74 and COPA in regulating the immunosuppressive microenvironment as well as the function of LGALS9 and HAVCR2 in regulating T-cell responses signified that they may be potential targets for the treatment of acute T-cell lymphoblastic leukemia." (PMID 39422621, 2024).
thymic carcinoma (3 papers, 2020 to 2024). Thymic carcinoma (TC) is a type of thymic epithelial neoplasm characterized by a high malignant potential. "For thymic carcinoma, the novel biomarkers of MSLN, CCL20, and SLC1A5 are identified and observed an elevated expression of LAG3 and HAVCR2 in malignant tumorn‐infiltrating mature T cells." (PMID 39258580, 2024).
Alzheimer disease (2 papers, 2021 to 2024). A progressive, neurodegenerative disease characterized by loss of function and death of nerve cells in several areas of the brain leading to loss of cognitive function such as memory and language. "According to a recent large-scale genome-wide association analysis for Alzheimer’s disease based on more than one million individuals, significant associations between HAVCR2 and Alzheimer’s disease were found." (PMID 38350848, 2024). "Interestingly, HAVCR2 and CAMP demonstrate higher scores compared to other genes, suggesting that M-GBBD has potential for predicting potential Alzheimer's disease-associated genes not yet annotated by DisGeNET." (PMID 38350848, 2024).
esophageal tumor (2 papers, 2019 to 2020). "HAVCR2 (TIM-3) exhibits a threefold increased expression in esophageal tumor samples compared to normal control samples." (PMID 31960110, 2020).
intracranial aneurysm (2 papers, 2025). "However, in calcific aortic valve disease (CAVD), only TIMD4 was up‐regulated, while in intracranial aneurysm (IA), only HAVCR2 showed increased expression." (PMID 40576208, 2025).
oropharyngeal carcinoma (2 papers, 2022 to 2023). Carcinoma, predominantly squamous cell, arising from the epithelial cells of the oropharynx. "We found that HAVCR2 gene promoter was hypomethylated in 77.8% of oral and oropharyngeal cancers." (PMID 37175405, 2023). "Most of the oral and oropharyngeal cancer samples were unmethylated in almost all the investigated gene promoters: EDARADD, GBP4, HAVCR2, HLA DPB1, IL12RB1, MARCO, and SIGLEC12." (PMID 37175405, 2023).
osteoarthritis (2 papers, 2024 to 2025). A noninflammatory degenerative joint disease occurring chiefly in older persons, characterized by degeneration of the articular cartilage, hypertrophy of bone at the margins and changes in the synovial membrane. "In addition, HAVCR2 genetic variations have been linked to increased risk of osteoarthritis, possibly because of upregulation of IFN-γ expression by CD4+ T cells." (PMID 38723011, 2024).
panniculitis (2 papers, 2020 to 2024). Inflammation of the subcutaneous adipose tissue. "Notably, of the 19 patients with HAVCR2 p.Y82C variant, 3 homozygotes (15.8%) had an episode of idiopathic HLH/HLH-like systemic illnesses before the appearance of panniculitis-like skin lesions with recurrent HLH/HLH-like systemic illnesses." (PMID 39538229, 2024).
prostate adenocarcinoma (2 papers, 2024 to 2025). "HAVCR2 expression was higher in most tumors, including glioblastoma and low-grade glioma (GBMLGG), lung adenocarcinoma (LUAD), prostatic adenocarcinoma (PRAD), and sarcoma (SARC)." (PMID 38590525, 2024).
Achalasia (1 paper, 2023). A disorder of esophageal motility characterized by the inability of the lower esophageal sphincter to relax during swallowing and by inadequate or lacking peristalsis in the lower half of the body of the esophagus. "Besides, many co-inhibitory molecules, including PDCD1, HAVCR2, LAG3, ICOS, PRDM1, and MAF, were markedly downregulated in TRM, supporting an activated cell state in achalasia." (PMID 37542039, 2023).
AIDS (1 paper, 2014). A syndrome resulting from the acquired deficiency of cellular immunity caused by the human immunodeficiency virus (HIV). "Although replication in additional independent samples will be necessary, data herein warrant further investigation into the role of HAVCR2 in the prevention and treatment of HIV-1/AIDS." (PMID 25180498, 2014).
aneuploidy (1 paper, 2025). Chromosomal disorder consisting of the presence a chromosomal abnormality in which there is an addition or loss of chromosomes within a set. "In addition, it was also found that some immune checkpoint genes (PDCD1, HAVCR2, TIGIT, LAG3) had high expression in high-risk group, which was related to a higher TIDE and aneuploidy scores than in the low-risk group." (PMID 39950044, 2025).